KRTAP29-1 (keratin associated like protein 29-1)
Synonyms: KAP29.2
Tractability: No criterion of Open Targets' tractability assessment is met for any kind of drug.
Gene: Protein-coding gene on chromosome 17 (41,301,826 to 41,302,851, reverse strand). Ensembl gene ENSG00000212658.
Pathways (Reactome):
Developmental Biology: Keratinization
Gene Ontology:
Molecular function: structural molecule activity
Cellular component: cytosol; keratin filament
Genetic constraint (gnomAD): Loss-of-function variants: 0 observed, 0.0964 expected, observed/expected ratio (o/e) 0, 90% interval 0 to 1.89. That is too few expected variants to judge how well the gene tolerates losing a copy. Missense variants: 413 observed, 425.45 expected, observed/expected ratio (o/e) 0.97, 90% interval 0.89 to 1.05. Synonymous variants: 138 observed, 159.39 expected, observed/expected ratio (o/e) 0.87, 90% interval 0.75 to 1.
Homologues: Orthologues: chimpanzee KRTAP29-1 (99% identical), macaque KRTAP29-1 (91% identical), pig KRTAP29-1 (71% identical), mouse Krtap29-1 (55% identical), rat Krtap29-1 (54% identical), mouse Gm10153 (23% identical).